MBNL1 (muscleblind like splicing regulator 1)
Diseases named in the same sentence as MBNL1 in open-access papers (continued):
Sharing a sentence is not in itself a finding about the gene and the disease.
Myotonia (50 papers, 2008 to 2025). An involuntary and painless delay in the relaxation of skeletal muscle following contraction or electrical stimulation. "ATP2A1 exon 22 exclusion is associated with muscle dysfunction, CLCN1 exon 7a inclusion is associated with myotonia, and MBNL1 exon 5 inclusion is associated with MBNL1 subcellular localization." (PMID 37111604, 2023). "Recent in vitro and in vivo studies demonstrated that PTM associates with the expanded triplets, preventing MBNL1 sequestration, decreasing the formation of nuclear foci and reducing myotonia in experimental models." (PMID 36613739, 2022). "Overexpression of Mbnl1 in skeletal muscle with an adeno-associated viral vector rescues disease-associated muscle hyperexcitability or myotonia in a transgenic mouse model for DM117,18." (PMID 32054946, 2020). "While further confirming the role of Mbnl1 loss of function in the onset of myotonia, these findings also hint at the involvement of additional disease intermediates in muscle pathology." (PMID 30050493, 2018). "Mbnl1 inactivation impacted primarily the skeletal muscle and caused pronounced myotonia, but it also resulted in DM1-like subcapsular cataracts, lack of motivation and apathy in knockout mice." (PMID 30050493, 2018). "RNA processing is disrupted, in part due to inactivation of the alternative splice regulator, MBNL1 which normally regulates splicing of several transcripts including Cncl1, a chloride channel associated with myotonia." (PMID 20360842, 2010). "Significantly, rescue experiments in DM1 model mice demonstrate that loss of Mbnl1 function is the key event of missplicing and myotonia." (PMID 18270582, 2008). "A previous study showed that 2-fold upregulation of MBNL1 protein by transduction of a recombinant adeno-associated viral vector reversed missplicing of Clcn1, Ldb3, Serca1, and Tnnt3, resulting in a significant reduction in myotonia in a DM1 mouse model." (PMID 32054946, 2020). "Downregulation of MBNL1 availability leads to aberrant regulation of alternative splicing of hundreds of genes, which causes various manifestations such as myotonia, progressive muscle wasting, cataracts, insulin resistance, cardiac arrhythmia, and intellectual deficits." (PMID 32054946, 2020). "To determine whether the microtranscriptome changes are specific to MBNL1 deficiency or are a consequence of muscle pathology (e.g. myotonia or muscle dystrophy), we assessed whether similar miRNA changes were observed in a mouse model of facioscapulohumeral muscular dystrophy (FSHD)." (PMID 39258536, 2024). "Indeed, the loss of MBNL proteins is responsible for myotonia in the context of human skeletal muscle and loss of MBNL1 function accounts for more than 80% of mis-splicing events and nearly 70% of expression defects in a murine model expressing 250 CTG repeats." (PMID 39682688, 2024). "Systemic administration of B-PMO targeting this repeat element causes the blocking of Mbnl1 sequestration, resulting in normal nuclear distribution and subsequent correction of abnormal RNA splicing, including for the chloride channel 1 gene, which is a primary contributor to myotonia." (PMID 37830609, 2023). "The limited MBNL1 availability leads to the aberrant regulation of alternative splicing of hundreds of genes, causing various clinical manifestations such as progressive muscle wasting, myotonia, insulin resistance, cardiac arrhythmia, cataracts, and intellectual deficits." (PMID 36510245, 2022). "From initial observation of Mbnl1−/−; ClC-1ΔE7a/ΔE7a mice cage behavior, it was clear that our goal of eliminating myotonia from this DM1 mouse line was successful." (PMID 41000779, 2025). "Overall, these changes remain consistent across the other hindlimb muscles tested, all of which have been shown to exhibit myotonia in the Mbnl1 knockout model of DM121." (PMID 41000779, 2025).
Myotonia (continued). "The Mbnl1 KO is characterized by muscle (such as myotonia), immune system and vision pathology, resulting in limited paths of exploration that preclude assessment of social interaction." (PMID 40259070, 2025). "The foci sequester muscleblind-like splicing regulator 1 (MBNL1), an RNA splicing protein, which in turn leads to misplicing events that induce, among other abnormalities, myotonia, insulin resistance and elevated cytoplasmic calcium levels." (PMID 39031377, 2024). "LR41;Mbnl1−/− double homozygous mice experience prominent, severe myotonia that can be exacerbated in the hindlimbs by briefly grasping the base of the tail." (PMID 37029100, 2023). "It has been previously shown that disaggregating RNA foci repletes free MBNL1, rescues DM1 spliceopathy, and alleviates associated symptoms such as myotonia." (PMID 36835205, 2023). "In a mouse model of DM1, subcutaneous administration of an antagomiR upregulated the expression of MBNL1, rescued splicing alterations, and improved grip strength and myotonia." (PMID 35205411, 2022). "Subcutaneous administration of anti-miR 23b in human skeletal actin long repeat mice upregulated the expression of MBNL1 and rescued splicing alterations, grip strength, and myotonia." (PMID 33291833, 2020). "MBNL1 overexpression was well-tolerated in skeletal muscle and early and long-term MBNL1 overexpression prevented CUG-induced myotonia, myopathy, and alternative splicing abnormalities in DM1 mice." (PMID 29946070, 2018). "Dual depletion of Mbnl1 and Mbnl3 also enhanced myotonia, muscle weakness and myopathy in skeletal muscle." (PMID 30050493, 2018). "Consistently, overexpression of Mbnl1 in skeletal muscle of the poly(CUG) mouse DM1 model rescues the myotonia phenotype concurrently with a restoration of the normal adult-splicing patterns." (PMID 30567354, 2018). "A Mbnl1 knock-out (KO) mouse model displays myotonia, missplicing of muscular transcripts and cataracts, which are all characteristic symptoms of DM1 disease." (PMID 27805016, 2016). "The average median score for myotonia was 2.5/3 for the TA expressing EGFP as compared to an average median score of 1.25/3 for the TA that expressed MBNL1-EGFP." (PMID 24039817, 2013). "Significantly, increased MBNL1 in skeletal muscle partially corrected myotonia and splicing defects present in these mice, demonstrating the responsiveness of the model to relevant therapeutic interventions." (PMID 24039817, 2013). "This notion is further supported by the results using the EDM1 mouse model where we were able to show that over-expression of MBNL1 was capable of partially correcting myotonia and some mRNA splicing defects, akin to the results obtained using the HSA-LR mice." (PMID 24039817, 2013). "Because myotonia was more severe following the depletion of Mbnl2, we first compared the Clcn1 splicing pattern in WT, Mbnl1 KO and Mbnl1−/−; Mbnl2+/− KO skeletal muscle." (PMID 24293317, 2013). "MBNL1 knockout mice show many of the same splicing problems and some of the phenotypic abnormalities associated with DM1, such as myotonia and cataracts." (PMID 24039817, 2013). "MBNL1 mutant mice show cataracts, myotonia, and other muscle abnormalities that closely resemble a number of DM1 pathological features, and they also share many of the splicing aberrations observed in transgenic mice expressing CUG repeats." (PMID 23637619, 2013). "Analysis of MBNL1-knock out mice showed that homozygous animals developed main symptoms of DM1: myotonia, muscular dystrophy and cataracts." (PMID 20885816, 2010). "DM1-associated defects are remarkably similar to those observed in Mbnl1 knockout mice and include myotonia, ocular cataracts, histological abnormalities, and the abnormal use of specific alternative exons." (PMID 18270582, 2008). "This supports the hypothesis that myotonia may account for some of portion of the altered transcript expression seen in Mbnl1 knockout mice." (PMID 41000779, 2025).
Myotonia (continued). "Exon 7a deletion restored ClC-1 channel function and eliminated myotonia in Mbnl1 knockout mice." (PMID 41000779, 2025). "The impact of myotonia on muscle performance in Mbnl1−/− mice was assessed by ex vivo force-contraction recordings in soleus muscles isolated from adult (4–6-month-old) WT, ClC-1ΔE7a, Mbnl1−/−, and Mbnl1−/−; ClC-1ΔE7a mice." (PMID 41000779, 2025). "Knockout studies in mice revealed that MBNL1 depletion results in myotonia." (PMID 40723324, 2025). "However, they found that Mbnl1−/−/Mbnl2+/− were viable (albeit with reduced survival), smaller in size, and had increased myotonia, weakness, and severe myopathy by 8–12 weeks of age." (PMID 38473933, 2024). "In the HSALR, a mouse model that expresses a human actinin transgene containing CTG repeats in their skeletal muscle, different types of ASOs were able to promote RNA foci reduction, MBNL1 redistribution, correction of abnormal splicing, and myotonia improvement." (PMID 37397246, 2023). "In complementary gain-of-function experiments, the overexpression of Mbnl1 in skeletal muscle, using a recombinant adeno-associated viral vector in a murine model expressing 250 CTG repeats (HSALR mice), rescued myotonia, hyperexcitability, and aberrant splicing." (PMID 36510245, 2022). "Overexpression of MBNL1 can reverse RNA missplicing and myotonia in a DM1 mouse model." (PMID 32463444, 2020). "Anti-miR treatment of each miRNA independently in DM1 myoblasts and DM1 mice increased MBNL1 levels, and in the latter this was linked to improvements in spliceopathy profile, histopathological signs, and functional myotonia without toxicity." (PMID 33291833, 2020). "By invoking simultaneous MBNL1 and 2 modulation, the miRNA approach can achieve significant and long-term improvement of DM1-linked phenotypes, including not only mis-splicing and myotonia, but also histopathology (central nuclei) and muscle strength recoveries." (PMID 31717488, 2019). "Furthermore, a mouse knockout (KO) for Mbnl1 reproduces myotonia, alterations in alternative splicing, and cataracts." (PMID 31717488, 2019). "Instead, enhanced myotonia was the result of the synergy between Clcn1 missplicing caused by Mbnl1 deletion alone, and defective CLCN1 translation, caused by combined inactivation of MBNL1 and MBNL3 proteins." (PMID 30050493, 2018). "Additionally, over-expression of MBNL1 or liberation of MBNL1 from ribonuclear foci has been show to correct the altered splicing and myotonia in DM1 cellular and animal models." (PMID 24039817, 2013). "In contrast, the Mbnl1−/− mice display hypo-activity (Figure 3Ciii) and a decreased response to foot shock (activity burst, Figure 3Diii), consistent with muscle weakness or myotonia." (PMID 20360842, 2010). "In Mbnl1−/− mice without myotonia, uniquely mis-spliced genes are predominantly associated with cytoskeleton organization and the Yap-Tead complex, comprising the transcription factor YAP1 and its coactivator TEAD1, both of which respond to mechanical stimuli (right dot plot)." (PMID 41000779, 2025). "Thus, Mbnl1−/−; Mbnl2+/− KOs recapitulate DM-relevant muscle weakness/wasting and myotonia." (PMID 24293317, 2013). "Although Mbnl1−/−; Mbnl2−/− double knockouts (DKOs) are embryonic lethal, Mbnl1−/−; Mbnl2+/− mice are viable but develop cardinal features of DM muscle disease including reduced lifespan, heart conduction block, severe myotonia and progressive skeletal muscle weakness." (PMID 24293317, 2013). "Moreover, adenoviral delivery of MBNL1 into CUG-transgenic mice partially corrects myotonia." (PMID 20885816, 2010). "Interestingly, Mbnl1−/−; ClC-1ΔE7a/+ mice with only a single allele with forced E7a exclusion, also lacked any evidence of myotonia, and thus for all physiologic experiments both heterozygote and homozygote ClC-1ΔE7a mice were used as indicated by either ClC-1ΔE7a or Mbnl1−/−; ClC-1ΔE7a." (PMID 41000779, 2025).
Myotonia (continued). "Notably, Mbnl1−/−; ClC-1ΔE7a muscle displayed a significantly reduced percent of fibers with central nuclei (~56% less) as compared to Mbnl1−/− samples (p = 0.0004), which indicates that myotonia may play a role in driving central nucleation in DM1 mice." (PMID 41000779, 2025). "In fact, 6aKC PMOs worked best for myotonia reduction and those DM1 alterations requiring long recovery periods after Mbnl1 levels are restored, such as central nuclei." (PMID 37744174, 2023). "It has been previously shown that disaggregating these RNA foci by antisense oligonucleotide (ASO) or morpholino repletes MBNL1, rescues the DM1 spliceopathy, and alleviates signs and symptoms including myotonia." (PMID 36835205, 2023). "The Muscleblind-like 1 knockout (Mbnl1−/−) mouse model of DM1 features a homozygous deletion of Mbnl1 exon 3, leading to deregulated alternative splicing and myotonia to a greater degree than in LR41 or LR20b8,23,24." (PMID 37029100, 2023). "In animal experiments, Mbnl1 knockout mice recapitulate the main clinical symptoms for DM1, such as myotonia, aberrant splicing, cataracts, cardiac dysfunctions, and progressive skeletal muscle weakness." (PMID 36510245, 2022). "MBNL1 upregulation in DM1 mice and DM1 drosophila is well tolerated without obvious side effects, and rescues several symptoms, such as myotonia, myopathy, and mis-splicing events." (PMID 36510245, 2022). "AICAR- and exercise-induced activation of AMPK in DM1 mice resulted in functional improvements and reduced myotonia, which were largely driven by a reduction in CUG foci, liberating MBNL1 and correcting several missplicing events." (PMID 35316212, 2022). "MBNL proteins are highly conserved and tightly regulated, and mice with Mbnl1/Mbnl2 deletion exhibit cardinal features of DM1, such as myotonia, myopathy and heart block." (PMID 33503262, 2021). "Firstly, administration of recombinant Mbnl1 protein to a HSALR mouse model of DM1, rescues myotonia and the splicing alterations characteristic of DM126." (PMID 27805016, 2016). "Consistent with our results, over expression of MBNL1 in transgenic mice expressing CTG tracts allows the rescue of both the splice defects and myotonia." (PMID 19092997, 2008). "We also observed changes in transcript splicing for several in the setting of or absence of myotonia in Mbnl1−/− mice, including tropomyosin isoforms, indicating a potential role of myotonia for regulating splicing changes in DM1." (PMID 41000779, 2025). "In HSALR mice, subcutaneous injection of gapmer ASOs significantly degraded expanded CUG transcripts as well as lncRNAs in skeletal muscle, reversing MBNL1 sequestration, myotonia, and mis-splicing without apparent off-target effects." (PMID 34867280, 2021). "Mbnl1−/− mice exhibit alternative splicing changes, myotonia, myopathy and cataracts, but do not have other DM-related phenotypes such as muscle weakness." (PMID 34125183, 2021). "The important role that MBNL1 plays in DM1 is supported by the Mbnl1 knockout mice phenotypes, which show several DM1 features including misregulated mRNA splicing, histopathological muscle changes, cataracts and myotonia." (PMID 30567354, 2018). "Similarly, knock-out of MBNL1 is sufficient to recapitulate muscle degeneration and RNA-splicing defects, whereas overexpression of MBNL1 prevents poly(CUG)-induced myotonia, myopathy, and splicing defects in DM1 mice." (PMID 25593321, 2015). "Importantly, MBNL1 overexpression ameliorates, muscle wasting in a Drosophila DM1 model, and myotonia and splicing aberrations in mouse models." (PMID 23637619, 2013). "Additionally, Mbnl1 overexpression reverses myotonia in transgenic HSALR mice, which express a CUGexp RNA in skeletal muscle, and transgenic MBNL1 overexpression mice are viable with normal muscle structure and function." (PMID 24293317, 2013).
Myotonia (continued). "Consistent with the involvement of MBNL proteins in the RNA gain of function mechanism, Mbnl1 knockdown mice showed DM1-like phenotypes including iridescent cataracts, myotonia and missplicing of muscle transcripts that had been reported altered in DM1 patients such as IR and CLC-1 pre-mRNA." (PMID 19516957, 2008). "Absence of myotonia improved rotarod performance in Mbnl1 KO mice." (PMID 41000779, 2025). "Furthermore, through deep RNA-seq we were able to directly assess the impact of myotonia on transcript expression and splicing in mice lacking functional Mbnl1." (PMID 41000779, 2025). "Interestingly, several splicing factors including Srsf6, Prpf39, Rbm7, Tra2b, Rbfox2, and Hnrnpu, exhibited alternative splicing in Mbnl1−/− mice with myotonia, but not in those without." (PMID 41000779, 2025). "Additionally, although homozygous Mbnl1ΔE3/ΔE3 knockout mice model the multisystemic features of DM pathology heterozygous Mbnl1+/ΔE3 mice are similar to wild type and do not develop myotonia or other skeletal muscle changes." (PMID 19680539, 2009). "In DM1 and DM2 individuals without clinical myotonia, splicing of MBNL2, MBNL1, CLASP1, and MAP3K4 showed changes intermediate between those with myotonia and UA subjects." (PMID 30254196, 2018). "In contrast, expression of a high number of copies of the DMPK 3’ UTR containing 5 CUG repeats leads to development of DM1-like phenotype (myotonia, cardiac conduction defects and muscular dystrophy) in the absence of nuclear CUG foci and in the absence of MBNL1 sequestration." (PMID 20885816, 2010).